MST1 (macrophage stimulating 1)
Diseases named in the same sentence as MST1 in open-access papers (continued):
Sharing a sentence is not in itself a finding about the gene and the disease.
heart disease (4 papers, 2013 to 2025). "Inhibition of MST1 emerges as a potential therapeutic strategy to protect against heart disease." (PMID 41282233, 2025). "Using gain- and loss-of-function genetic models, it was shown that the Hippo-YAP signaling pathway components Mst1/2, Sav1, Lats1/2, NF2, and downstream transcriptional regulators YAP and Tead1 regulate cardiac gene expression, cardiomyocyte proliferation, and cardiac disease status." (PMID 32938943, 2020).
neurological diseases (3 papers, 2018 to 2022). "MST1 has been shown to be upstream of nuclear factor- (NF-) κB, a well-established conserved factor, for regulating neuroinflammation in many neurological diseases." (PMID 30018671, 2018). "Mst1 was identified as a critical factor in the development of neurological diseases." (PMID 35656021, 2022). "We suggest a more detailed and mechanistic approach to elucidate MST1 signaling in various neurological diseases and that inhibition of this signaling pathway may provide a new therapeutic avenue." (PMID 31117242, 2019).
gastrointestinal tumors (2 papers, 2022 to 2024). "On the basis of these findings, we further developed a synthetic lethality therapy in which the STRIPAK assembly was targeted via a combination of approaches to recover the kinase activity of MST1/2 and therefore resensitize gastrointestinal tumors to the effects of PARPi." (PMID 35290241, 2022). "Taken together, these results demonstrated that targeting of STRIPAK could recover the kinase activity of MST1/2, which, in combination with PARPi, could elicit strong synthetic lethality in human gastrointestinal tumors." (PMID 35290241, 2022). "Adoptive transfer of AKT- or MST1-overexpressing macrophages, or Keap1 disruption in myeloid-specific TSC1-knockout mice promoted NRF2 activation but reduced TLR4 activity and mitigated I/R-induced liver inflammation." (PMID 38360839, 2024).
hematologic malignancies (2 papers, 2024 to 2025). "Previous studies have shown that low levels of YAP1 can block ABL1-induced apoptosis in hematological malignancies, while the genetic inactivation of MST1 restores YAP1 levels and causes cell death, both in vitro and in vivo." (PMID 40573272, 2025).
hematopoietic neoplasms (2 papers, 2018 to 2025). "Taking into account the results obtained in our work, we consider the investigation of the possibility of using the MST1/2 kinase inhibitors in the treatment of hematologic tumors extremely promising." (PMID 40573272, 2025). "We have shown that targeting the MST1/2 kinases, which are the key molecules in this signaling pathway, may be an effective approach to the treatment of hematologic tumors." (PMID 40573272, 2025). "In this study, we show that targeting MST1/2 kinases, the key molecules in the Hippo signaling pathway, may prove to be an effective way to treat hematologic tumors." (PMID 40573272, 2025). "The use of MST1/2 kinase inhibitors could be highly promising for complex therapy of hematological tumors." (PMID 40573272, 2025). "Unlike solid tumors, knocking down MST1 or increasing YAP1 expression in hematopoietic tumors inhibits growth and leads to apoptosis." (PMID 40573272, 2025). "Third, Mst1/2 knockout in HSCs did not induce hyperplasia or spontaneous hematopoietic neoplasms up to the time of death (D.H. Lee, D. Lee and D.S. Lim, unpublished data)." (PMID 29343826, 2018).
inflammation (2 papers, 2018 to 2020). Aberrant reaction of the microcirculation characterized by movement of fluid and leukocytes from the blood into extravascular tissues. "As a result of cardiac inflammation, the IL6, TNFα and MCP1 transcription levels were also higher in post-infarcted myocardium, and this effect was inhibited by Mst1 knockout." (PMID 29760744, 2018).
kidney diseases (2 papers, 2022). "Future studies need to explore strategies (such as modulation of YAP, LATS1/2, and MST1/2 expression) that will help make clinical diagnosis more accurate, more sensitive, and faster to allow assessment of the progress and improve the treatment and prognosis of kidney diseases." (PMID 36483738, 2022).
metabolic disease (2 papers, 2019 to 2023). A congenital disorder (due to inherited enzyme abnormality) or acquired (due to failure of a metabolically important organ) disorder resulting from an abnormal metabolic process. "In recent years, MST1 has been shown to be closely related to cardiovascular and metabolic diseases." (PMID 31816893, 2019).
head and neck tumors (1 paper, 2024). "PAX3::FOXO1 inhibits the Hippo/MST1 signaling pathway, and genetic removal of Mst1/Mst2 Hippo pathway members in the Myf6-Cre Pax3::Foxo1 mouse model increased the frequency of head and neck tumors." (PMID 38916046, 2024).
infectious disease (1 paper, 2012). A disorder directly resulting from the presence and activity of a microbial, viral, or parasitic agent in humans. "The infectious diseases seen in some but not all MST1-deficient patients, including susceptibility to EV-HPV lesions, may reflect clinical exposure or the impact of modifier genes." (PMID 22952854, 2012).
retinopathy (1 paper, 2019). "To see whether endothelial MST1 and FOXO1 has a significant role in pathologic angiogenesis, we employed an oxygen-induced retinopathy (OIR) model." (PMID 30783090, 2019).
MST1 also shares sentences with these, for which no sentence is quoted: neuroblastoma (3 papers); adenocarcinoma (2); autoimmune pancreatitis (2); injury (2); multiple sclerosis (2); ulcerative colitis (2); age-related macular degeneration (1); allergies (1); Anxiety (1); asthma (1); ataxia telangiectasia (1); atrial fibrillation (1); autoimmune haemolytic anaemia (1); bipolar disorder (1); bladder cancers (1); bleeding disorder (1); brain injury (1); cerebral infarction (1); cholangiocarcinoma (1); circulatory arrest (1); Clouston syndrome (1); co-infection (1); digestive system disorder (1); Disc Degeneration (1); epidermodysplasia verruciformis (1); epithelioid hemangioendothelioma (1); Failure to thrive (1); fibrosarcoma (1); Gestational diabetes mellitus (1); glaucoma (1).
A further 52 diseases each share a sentence with MST1 in 1 paper.